SDC2 (syndecan 2)
Diseases named in the same sentence as SDC2 in open-access papers (continued):
Sharing a sentence is not in itself a finding about the gene and the disease.
prostate carcinoma (9 papers, 2012 to 2023). A carcinoma that arises from epithelial cells of the prostate gland. "Result showed that COL3A1 and SDC2 were found to be the highest risk factors of prostate cancer, followed by RAC1 and PTPRF." (PMID 34229299, 2021). "In addition, overexpression of SDC1 and SDC2 were associated with more aggressive in prostate cancer and MDK-LRP1 will induce the differentiation of immunosuppressive macrophages." (PMID 37065499, 2023). "In Gleason 3-5 prostate cancers α2β1 integrin is significantly decreased, suggesting that the expression levels of α2β1 and syndecan 2 may be linked in vivo, too." (PMID 30197754, 2018). "Interestingly, syndecan 2 is strongly up regulated in prostate cancers with high Gleason score." (PMID 30197754, 2018). "According to these results, we hypothesized that these expression patterns (and secretion patterns) might be reflected in vitro; however, immunofluorescence analyses only confirmed a granular cytoplasmic localization of SDC-2 (comparable to SDC-2 localization in prostate cancer cells)." (PMID 22471946, 2012). "In contrast, SDC1 mediates EMT in prostate cancer and the expression of SDC1 (and also SDC2) is correlated with EMT markers (E-cadherin, β-catenin) in prostate cancer." (PMID 34282767, 2021). "Our results revealed that COL3A1, SDC2 and FN1 are dramatically enriched in the ECM-receptor interaction pathway, which may play a key role in the process of tumor development and bone metastasis of prostate cancer." (PMID 34229299, 2021).
fibrosarcoma (8 papers, 2009 to 2025). A malignant mesenchymal fibroblastic neoplasm affecting the soft tissue and bone. "The inhibition of syndecan-2 has also been reported to abolish TGF-β-dependent adhesion with decreased Smad2 activation in fibrosarcoma cells." (PMID 31600983, 2019). "This proteoglycan is often overexpressed in adenocarcinoma cells, whereas mesothelioma and fibrosarcoma cells express syndecan-2 and syndecan-4 more abundantly." (PMID 24392351, 2013). "According to earlier studies, both syndecan-1 and syndecan-2 promote malignancy of HT-1080 human fibrosarcoma cells, by increasing the proliferation rate and the metastatic potential and migratory ability, respectively." (PMID 22745764, 2012). "Malignant mesothelioma and fibrosarcoma are aggressive tumors of mesenchymal origin, and they express a characteristic PG profile, in which syndecan-2 and -4 are the main cell-surface PGs." (PMID 19802384, 2009). "Similarly, in fibrosarcoma cells, syndecan 2 regulates TGFβ2 transcriptional regulation via Smad signaling to facilitate fibrosarcoma cell adhesion." (PMID 39334952, 2024). "Overexpression of syndecan-1 resulted in a downregulation of syndecan-2 and upregulation of syndecan-4 in epithelioid mesothelioma cells, whereas in epithelioid fibrosarcoma cell line syndecan-2 was upregulated, and in a sarcomatoid fibrosarcoma cell line syndecan-4 was downregulated." (PMID 24392351, 2013). "Syndecan 2 directly mediates IGFI-induced extracellular signal-regulated kinase 1/2 (ERK1/2) activation, recruits ezrin, contributes to actin polymerization and ezrin–actin membrane localization, and ultimately facilitates the progression of IGFI-dependent fibrosarcoma cell migration." (PMID 39334952, 2024).
osteosarcoma (7 papers, 2014 to 2023). A usually aggressive malignant bone-forming mesenchymal neoplasm, predominantly affecting adolescents and young adults. "Of note, SDC2 contributes to osteosarcoma cell response to cytotoxic agents through interactions with Wnt/β-catenin signaling." (PMID 29118673, 2017). "Overexpression of SDC2 sensitized human osteosarcoma cells to apoptosis induced by chemoagents, as well the fibroblast cells to apoptosis induced by serum-withdrawal." (PMID 28977882, 2017). "SDC2 was known to induce cell apoptosis in osteosarcoma through JNK signaling." (PMID 28977882, 2017). "Previous studies have proved that miR-20a-5p suppressed SDC2 and KIF26B, leading to a reduction in the multi-drug resistance of osteosarcoma." (PMID 36769824, 2023).
pancreatic cancer (7 papers, 2012 to 2023). "Syndecan-2 also plays a significant role in pancreatic cancer, working as an invasive-associated gene that, as well as syndecan-1, cooperates with KRas to induce the invasive phenotype." (PMID 33669066, 2021). "For example, SDC2 contributed to the malignancy of pancreatic cancer cells by regulating the K-ras/MAPK pathway 24, and enhanced the invasiveness of lung adenocarcinoma by upregulating the NF- κB signaling pathway." (PMID 37496999, 2023). "For example, studies of lung adenocarcinoma, lung fibrosarcoma, as well as cancers of pancreas and breast found that SDC2 promoted cell invasion, tumor growth, and/or immune evasion 22, 24-27." (PMID 37496999, 2023). "Now, using the same ex vivo model, we identified syndecan-2 (SDC-2) expression to be up-regulated in pancreatic cancer cell clones which have an increased perineural invasive capacity." (PMID 22471946, 2012). "Using an ex vivo model of perineural invasion in pancreatic cancer, we have found upregulation of syndecan-2 in nerve-invasive pancreatic cancer cell clones." (PMID 22471946, 2012). "In conclusion, we demonstrate that syndecan-2 is an important mediator of pancreatic cancer cell invasiveness and that it cooperates with oncogenic K-ras in the induction of a (more) malignant phenotype." (PMID 22471946, 2012). "The significance of SDC2 expression in pancreatic cancer is still debated." (PMID 34249755, 2021). "Using this model, we found syndecan-2 upregulation in nerve-invasive pancreatic cancer cell lines." (PMID 22471946, 2012). "Most importantly, we found that syndecan-2 modulates invasiveness of pancreatic cancer cells in culture and may interferes with K-ras/MAPK signaling as one of the predominantly deregulated pathways in PDAC." (PMID 22471946, 2012). "Thus, in a next step, we analyzed the function of SDC-2 in pancreatic cancer cells in vitro." (PMID 22471946, 2012). "It has been demonstrated that in pancreatic cancer cell lines with wild-type KRAS, RACK1 and syndecan-2 are interacting." (PMID 33669066, 2021). "Additionally, syndecan-2 (SDC-2) promotes perineural invasion and cooperates with K-ras to induce an invasive pancreatic cancer cell phenotype." (PMID 36418844, 2023). "SDC1, SDC2 and SDC3 have been described to have a role in pancreatic cancer." (PMID 34249755, 2021). "Furthermore, we have silenced SDC2 in T3M4 and Panc1 pancreatic cancer cell lines." (PMID 22471946, 2012).
pulmonary fibrosis (7 papers, 2012 to 2024). Chronic progressive interstitial lung disorder characterized by the replacement of the lung tissue by connective tissue, leading to progressive dyspnea, respiratory failure, or right heart failure. "In conclusion, our findings suggest that SDC2 significantly attenuates the development of pulmonary fibrosis in an inflammatory arthritis mouse model and limits myofibroblast differentiation and extracellular matrix gene expression in RA-ILD fibroblasts." (PMID 35181688, 2022). "We have demonstrated that SDC2-mediated CD148 activation inhibits experimental lung fibrosis by regulating PI3K/Akt/mammalian target of rapamycin (mTOR) signaling, thereby increasing autophagy and decreasing levels of p62 and subsequent NF-κB inactivation." (PMID 35181688, 2022). "A recent study suggested that syndecan-2 attenuates radiation-induced pulmonary fibrosis and inhibits fibroblast activation by regulating the PI3K/Akt/ROCK pathway via CD14833." (PMID 31754474, 2019). "Syndecan-2 (Sdc2) was found to be over-expressed in skin and lung fibrosis, although it was recently reported to ameliorate radiation-induced fibrosis in transgenic mice." (PMID 30621228, 2019). "Since IGFBP-3 is over-expressed in fibrotic tissues, we examined SDC2 levels in skin and lung tissues of patients with systemic sclerosis (SSc) and lung tissues of patients with idiopathic pulmonary fibrosis (IPF)." (PMID 22900087, 2012). "Compared to normal lung, SDC2 protein was increased in fibrotic lung tissues of patients with IPF and SSc-associated pulmonary fibrosis." (PMID 22900087, 2012). "Interestingly, while involved in tissue repair, the expression of SDC2 is increased in alveolar macrophages in patients with pulmonary fibrosis, and exerts antifibrotic effects in experimental models of lung fibrosis." (PMID 34355516, 2022). "Based on these results and our prior studies, SDC2 may represent a promising therapeutic agent for the treatment of lung fibrosis." (PMID 35181688, 2022). "Our results further detail the importance of in vivo regulation of PAD2 by SDC2, as transgenic mice that overexpress human SDC2 displayed decreased bleomycin-induced pulmonary fibrosis and reduced PAD2 expression after bleomycin-induced lung injury in an inflammatory arthritis model." (PMID 35181688, 2022). "Since IGFBP-3 induces SDC2 expression and IGFBP-3 expression and deposition is increased in IPF, we used immunohistochemistry to detect SDC2 protein in vivo in IPF lung tissues and those from patients with SSc-associated pulmonary fibrosis." (PMID 22900087, 2012). "Although we demonstrate that the antifibrotic effects of SDC2 in vivo are associated with decreased PAD2 expression in the lung, an important consideration is that there is limited evidence that PAD2 is directly involved in the development of pulmonary fibrosis in our model." (PMID 35181688, 2022). "Interestingly, a synthetic 18 amino-acid peptide derived from the SDC2 ectodomain (SDC2-pep) is sufficient to bind and activate CD148 and use of this peptide has been proposed as a potential therapeutic strategy for idiopathic pulmonary fibrosis." (PMID 38255894, 2024). "Finally, we demonstrate that SDC2-transgenic mice express lower levels of PAD2 and are protected from lung fibrosis after bleomycin-induced lung injury in a model of inflammatory arthritis." (PMID 35181688, 2022). "Recently, we have extended the knowledge of the roles of SDC2 and CD148 in pulmonary fibrosis." (PMID 35181688, 2022). "Furthermore, SDC2-transgenic mice exposed to bleomycin-induced lung injury in an inflammatory arthritis model expressed lower levels of PAD2 and were protected from the development of pulmonary fibrosis." (PMID 35181688, 2022).
Sepsis (7 papers, 2015 to 2024). Sepsis is defined as life-threatening organ dysfunction caused by a dysregulated host response to infection. "Silencing of SDC2 resulted in a loss of survival benefit, more tissue cell death, and less bacterial clearance when administered after the onset of polymicrobial sepsis compared with shSCR hMSCs." (PMID 34355516, 2022). "Administration of human MSCs silenced for SDC2 in experimental sepsis resulted in decreased bacterial clearance, and increased tissue injury and mortality compared with wild‐type MSCs." (PMID 34355516, 2022). "In conclusion, this study demonstrates an important role for endogenous SDC2 on bone marrow‐derived hMSC function (both cellular and paracrine actions) during experimental sepsis." (PMID 34355516, 2022). "Collectively, these data advance our understanding of how SDC2 promotes hMSC function during experimental polymicrobial sepsis." (PMID 34355516, 2022). "Since MSCs are also known to modulate inflammation and tissue repair, we propose that SDC2 plays an important role in MSC function during sepsis to alleviate organ dysfunction." (PMID 34355516, 2022). "Collectively, these data demonstrate the importance of SDC2 for cellular and paracrine function of human MSCs during sepsis." (PMID 34355516, 2022). "They determined that the loss of SDC2 decreases inflammatory resolution, bacterial clearance, and neutrophil phagocytosis, concluding that SDC2 is critical for the cellular and paracrine functions of therapeutically delivered MSCs during sepsis; the mechanisms by which this occurs remain undefined." (PMID 38912739, 2024). "Since SDC1 and SDC4 are known to influence the cargo of EVs, we cannot exclude the impact of SDC2 on the composition of MSC‐derived EVs and this influence on sepsis pathobiology." (PMID 34355516, 2022). "While these studies used SDC2 as a marker for isolation of a homogeneous population of MSCs, the purpose of our study was to determine whether SDC2 plays an important role in MSC biology and function during experimental sepsis." (PMID 34355516, 2022).
breast tumor (6 papers, 2006 to 2023). "Overexpression of SDC2 in TASCs causes a significant increase in breast tumour growth at Day 17 after initial detection of palpable tumour growth (P < .01)." (PMID 33152121, 2021). "In mouse xenografts, it was further shown that HMGA2 promotes breast tumor growth, survival, and metastasis by inducing syndecan-2 (SDC2) via a miR-200-independent mechanism." (PMID 33668453, 2021). "In patients with ER‐negative breast cancer, high SDC2 RNA expression in breast tumours correlates with poor prognosis." (PMID 33152121, 2021). "Immunohistochemistry for syndecan-2 and its interacting partner, caveolin-2 was performed on human breast tumor tissue arrays." (PMID 25623282, 2015). "A very recent study illustrated that syndecan-2 depletion in MDA-MB231 derived 1833 cell line with enhanced bone tropism led to inhibition of breast tumor growth and metastasis to bone in a mouse xenograft model, in part through enhanced apoptosis." (PMID 25623282, 2015). "Previous data indicate that the inhibition of epithelial or stromal SDC2 with SDC2 peptides retards breast tumor growth and metastasis, as well as retraining tumor evasion (via downregulation of TGFβ-regulated programmed death ligand 1 and CXCR4) in a xenograft mouse model." (PMID 36980680, 2023). "HMGA2 has been suggested to mediate breast tumor metastasis by promoting the expression of LOX and syndecan-2." (PMID 25868853, 2015). "However, there is no previous evidence for involvement of a syndecan-2/caveolin-2 axis in breast tumor cell metastasis." (PMID 25623282, 2015).
atherosclerosis (5 papers, 2014 to 2025). A disease characterized by the build-up of fatty material and calcium deposition in the arterial wall resulting in partial or complete occlusion of the arterial lumen. "Of them, Ctnnd2, Dap, Marchf6, Cmbl, Sdc2, Cpq, Stk3, Vps13b, Cox6c, Grhl2, Fzd6, Cthrc1, Lrp12, and Zfpm2 showed associations or had functions related to atherosclerosis or obesity." (PMID 40362477, 2025). "After uncovering the high expression of SDC2 in ACS, we next aimed to investigate the regulatory mechanism of SDC2 in atherosclerosis by silencing SDC2 in mice via lentivirus." (PMID 32765295, 2020). "Initially, findings from the current study revealed that miR-9 was poorly-expressed and SDC2 was highly-expressed in atherosclerosis." (PMID 32765295, 2020). "However, the effects of miR-9 targeting SDC2 via the FAK/ERK signaling pathway on atherosclerosis in ACS remain to be unclear." (PMID 32765295, 2020). "Taken together, our data revealed that the up-regulation of miR-9 could potentially relieve atherosclerosis in ACS by down-regulating SDC2 via inhibition of the FAK/ERK signaling pathway." (PMID 32765295, 2020). "SDC2 was highly-expressed, while miR-9 was poorly-expressed in atherosclerosis." (PMID 32765295, 2020). "Besides, miR-9 may serve as a negative regulator of SDC2 to suppress atherosclerosis in ACS through inhibition of the FAK/ERK signaling pathway." (PMID 32765295, 2020). "Up-regulation of miR-9 reduced aortic plaque area, the proliferation of collagen fibers, Mac-3-labeled macrophages and levels of IL-6, IL-1β, and TNF-α by suppressing SDC2 and the FAK/ERK signaling pathway, thereby ameliorating atherosclerosis in ACS mice." (PMID 32765295, 2020). "In conclusion, the current study provides evidence that miR-9 retards atherosclerosis by repressing SDC2 and the FAK/ERK signaling pathway, highlighting a new theoretical basis for the treatment of atherosclerosis." (PMID 32765295, 2020). "The identification of the syndecan-2 adhesion regulatory domain as a strong negative regulator of angiogenesis mean that both it and its binding partner CD148 are potential novel therapeutic targets in pathologies where angiogenesis is a feature, such as atherosclerosis, arthritis and cancer." (PMID 25179601, 2014).
colorectal neoplasm (4 papers, 2017 to 2021). A benign or malignant neoplasm that affects the colon or rectum. "Our finding is in accordance with previous research that supports the feasibility of SDC2 as a methylation biomarker for the detection of colorectal neoplasms, and validated its clinical relevance in two Taiwanese institutions." (PMID 33393623, 2021). "On the other hand, considering that not all gastric and liver cancer patients were verified with colonoscopy as colorectal neoplasm-free, SDC2 methylation-positive in those patients might indicate that they have colorectal neoplasm." (PMID 30876480, 2019).
mesothelioma (4 papers, 2012 to 2022). A usually malignant and aggressive neoplasm of the mesothelium which is often associated with exposure to asbestos. "In addition, others found in STAV-AB mesothelioma cells that transfection of syndecan-1– contrary to the case in HT-1080– downregulates syndecan-2 expression." (PMID 22745764, 2012). "Importantly, immunohistochemical staining of SDC2 and TCF7L1 in metastatic MESO tissue was more intense than that in nonmetastatic mesothelioma tissue, and this difference reached statistical significance (P < 0.05, Welch's t-test)." (PMID 35127947, 2022).
Lewis lung carcinoma (3 papers, 2013 to 2020). "For example, in Lewis lung carcinoma, clones with a low metastatic potential contain high levels of SDC2, whereas, in highly metastatic clones, SDC2 overexpression reduces the invasive potential of cells due to the binding of HS chains to the fibronectin." (PMID 32916872, 2020). "SDC2 also cooperates with α5β1 integrin for regulation of actin-cytoskeletal organization in cell adhesion to fibronectin in Lewis lung carcinoma-derived metastatic cells, thus affecting their invasive capacity." (PMID 32916872, 2020). "Kusano and colleagues demonstrated that the induction of stress fiber formation in Lewis lung carcinoma-derived P29 cells during adhesion to fibronectin requires cooperation between integrin α5β1 with cell surface heparan sulfate from syndecan-2." (PMID 23705906, 2013).
metastatic disease (3 papers, 2012 to 2023). "In terms of metastatic disease there was variable level of association seen in the CMI values with a significant association seen only in the ITGA4 and SDC2 individual genes." (PMID 37264006, 2023).
Neuroendocrine Tumors (3 papers, 2014 to 2021). "Moreover, SDC2 has been found to be positively associated with the differentiation level and prognosis of neuroendocrine tumours, which is consistent with our findings." (PMID 33892730, 2021).
triple-negative breast carcinoma (3 papers, 2015 to 2026). An invasive breast carcinoma which is negative for expression of estrogen receptor (ER), progesterone receptor (PR), and human epidermal growth factor receptor 2 (HER2). "A closer examination of 47 triple negative breast cancer cases showed a significant correlation in the expression of syndecan-2 and caveolin-2." (PMID 25623282, 2015).
autism (2 papers, 2016 to 2021). Persistent deficits in social interaction and communication and interaction as well as a markedly restricted repertoire of activity and interest as well as repetitive patterns of behavior. "This suggest that Syndecan-2 and dendritic spine dysgenesis are related to autism." (PMID 27089953, 2016). "A female with mental retardation, multiple exostoses, and autism was shown to have an X;8 translocation, involved in the GRPR gene, and the SDC2 gene which codes Syndecan-2." (PMID 27089953, 2016).
fibrosis (2 papers, 2012 to 2022). the formation of excess fibrous connective tissue in an organ or tissue in a reparative or reactive process. "This is the first report describing elevated levels of SDC2 in fibrosis." (PMID 22900087, 2012).